SIRT1 (sirtuin 1)
Diseases named in the same sentence as SIRT1 in open-access papers (continued):
Sharing a sentence is not in itself a finding about the gene and the disease.
autoimmune disease (continued). "Sirt1 is a protein deacetylase that plays crucial role in inflammation and autoimmune diseases." (PMID 27034698, 2016). "Our previous study has demonstrated that Sirt1 is involved in periphery T cell tolerance; ablation of Sirt1 in T cells could induce hyper-activation of T cells and lead to spontaneous autoimmune disease." (PMID 24073240, 2013). "Therefore, SIRT1 inhibition, via nicotinamide or EX-527, has the potential to both induce Treg cells and inhibit Th17 cell differentiation, affecting both sides of the disturbed immune balance in autoimmune diseases such as JIA." (PMID 30792714, 2019). "Salmonella infection disrupts SIRT1/AMPK checkpoint control of mTOR to impair autophagy, and alterations of autophagy contribute to the progression of various autoimmune diseases, including systemic lupus erythematosus (SLE)." (PMID 38835801, 2024). "Due to its ability to activate SIRT1, RSV is able to relieve inflammatory symptoms in several experimental models of autoimmune diseases, such as type I diabetes, encephalomyelitis, and rheumatoid arthritis." (PMID 35056739, 2022). "SIRT1 deletion in CD4 T cells or its pharmacological inhibition by nicotinamide suppresses Th17 differentiation and protects against autoimmune diseases." (PMID 34828304, 2021). "Overall, most studies suggest a pro-inflammatory role for SIRT1 in CD4+ T cells, and especially Treg cells, in the setting of autoimmune diseases." (PMID 30792714, 2019). "As sex hormones contribute to many autoimmune diseases including SLE, SS and AS, we compared levels of anti-SIRT1 antibodies between male and female AS patients." (PMID 30558548, 2018). "Importantly, SIRT1-dependent control of Th9 cells differentiation appears to have a key role on anti-tumor immunity and allergic pulmonary inflammation, suggesting that targeting sirtuins could be exploited as potential therapies for inflammatory and autoimmune diseases." (PMID 34828304, 2021). "Furthermore, global knockout of SIRT1 inhibits production of pro-inflammatory T helper 17 (Th17) cells and ameliorates EAE clinical scores in Th17 cell-mediated autoimmune diseases." (PMID 30416425, 2018). "However, the SIRT1-regulated signaling pathway of these hub genes (ESR1) in autoimmune diseases has not been reported." (PMID 38835801, 2024).
diabetic retinopathy (41 papers, 2015 to 2026). "In diabetic mice SIRT1 exerts an antiangiogenic role in diabetic retinopathy via microRNA (miR)-20a elevation and yes-associated protein/HIF-1α/vascular endothelial growth factor A (YAP/HIF-1α/VEGFA) downregulation." (PMID 41011644, 2025). "Many degenerative ocular diseases such as cataracts, macular degeneration, diabetic retinopathy (DR), glaucoma, and optic neuritis are associated with a downregulation of Sirtuin-1 (SIRT-1)." (PMID 38258134, 2024). "The loss of SIRT1 due to HG-induced PARP1 activation is a crucial mechanism regulating NF-κB-MMP9-mediated mitochondrial dysfunction in diabetic retinopathy." (PMID 39598406, 2024). "In this case‐control study 398 individuals including 300 patients with T2DM (100 T2DM without complication, 100 diabetic neuropathy patients and 100 patients with diabetic retinopathy) and 98 healthy subjects were studied for SIRT1 rs3758391 T > C variants." (PMID 39474345, 2024). "Moreover, SIRT1 deficiency has been associated with increased oxidative stress, as well as progression of diabetic retinopathy and cognitive dysfunction." (PMID 39944232, 2024). "SIRT1 has an important role in ocular morphogenesis and retinal development, and is associated with cataracts, corneal diseases, age-related macular degeneration, diabetic retinopathy, glaucoma, and optic neuritis." (PMID 38254630, 2023). "Resveratrol alleviates reactive oxygen species and inflammation in diabetic retinopathy via the SIRT1/HMGB1 pathway, which regulates ferroptosis." (PMID 41198625, 2025). "The link between reduced SIRT1 levels and diabetic retinopathy (DR) has prompted the exploration of natural therapeutic compounds that act as SIRT1 agonists." (PMID 40006077, 2025). "In streptozotocin-induced diabetic retinopathy, upregulation of SIRT1 by stachydrine increases autophagy to reduce ROS and inflammation in RMECs." (PMID 39598406, 2024). "Various other miRs targeting SIRT1 have been investigated in the microcirculation, with diabetic retinopathy being a major focus." (PMID 39598406, 2024). "Various organic SIRT1 modulators have been shown to protect against streptozotocin-induced diabetic retinopathy models." (PMID 39598406, 2024). "Our findings suggest a protective role for SIRT1 C allele against T2DM and diabetic neuropathy and diabetic retinopathy." (PMID 39474345, 2024). "Downregulation of SIRT1 results in decreased autophagy and increased apoptosis, leading to the development of coronary microvascular dysfunction and diabetic retinopathy." (PMID 39598406, 2024). "For the first time we evaluated the SIRT1 gene variants in T2DM complications, diabetic neuropathy and retinopathy, and found the SIRT1 rs3758391 is associated with decreased risk of T2DM, diabetic neuropathy and diabetic retinopathy." (PMID 39474345, 2024). "In diabetic retinopathy, gliquidone regulated Notch-mediated angiogenesis to alleviate retinal injury via SIRT1." (PMID 39598406, 2024). "The restoration of SIRT1 activity has promise not only for preventing diabetic retinopathy development but also for reversing damage, given its epigenetic mode of action." (PMID 37627644, 2023). "SIRT1 expression is downregulated in the diabetic mouse retina, and its overexpression protects against the development of diabetic retinopathy." (PMID 37627644, 2023). "Hif-1α is a key mediator and target of retinal neovascularization and diabetic retinopathy, and during hypoxia, Sirtuin 1 (Sirt1) is downregulated, which allows the acetylation and activation of Hif-1α." (PMID 35346383, 2022). "Fenofibrate was found to attenuate diabetic retinopathy by endorsing SIRT1 activation to reduce the NF-κB activity in the retinal tissues of diabetic rats." (PMID 34071497, 2021).
diabetic retinopathy (continued). "Another research found that hsa-miR-34a promotes vascular endothelial cell apoptosis in diabetic retinopathy by targeting SIRT1." (PMID 34948403, 2021). "Action-mechanism pathways behind the retinoprotective effects of BGP-15 were outlined by our Western Blot results: BGP-15 is able to modify the expression of sirtuin 1 and matrix metalloproteinase 9 enzymes to alleviate the symptoms of diabetic retinopathy." (PMID 32204537, 2020). "Although the mechanistic roles of mitochondrial SIRTs have not been well studied in the context of chronic diabetic complications, we have previously demonstrated a potential role for SIRT1 in diabetic retinopathy (Mortuza, Feng, & Chakrabarti, 2014)." (PMID 32026628, 2020). "We found that APS functioned to up-regulate SIRT1 in high glucose-induced diabetic retinopathy and metabolic memory models via inhibiting miR-204 and subsequent ER stress as well as apoptosis." (PMID 31894851, 2020). "It has been demonstrated that miR-195 plays a major role in diabetic retinopathy by downregulating sirtuin 1 (SIRT1) and anti-apoptotic protein." (PMID 30347712, 2018). "tiRNA-Val, derived from mature tRNA-Val, is upregulated in human RMECs under HG conditions, decreasing SIRT1 expression, and ensuing HIF-1α upregulation enhanced RMEC proliferation, suggesting a role for tiRNA-Val in diabetic retinopathy-associated pathological angiogenesis." (PMID 39598406, 2024). "The C allele of SIRT1 reduced the risk of T2DM, diabetic neuropathy and diabetic retinopathy." (PMID 39474345, 2024). "The anti-inflammatory role of miR-204 has been recently elucidated in rats with diabetic retinopathy where the effect was likely mediated through Bcl-2 and SIRT1 upregulation, thus providing insight into another potential mechanistic pathway underlying this condition." (PMID 39488562, 2024). "However, recent evidence shows that SIRT1 also suppresses stress-induced pathological micro-angiogenesis, such as that observed in diabetic retinopathy." (PMID 39598406, 2024). "Likewise, SIRT1/Notch1 modulation was earlier stated to improve inflammation and oxidative stress in the model of diabetic retinopathy in rats." (PMID 37934372, 2023). "The multifunctional deacetylase SIRT1 is also involved in protection against diabetic retinopathy." (PMID 37627644, 2023). "The levels of Bcl-2 and SIRT1 could be upregulated by miR-204 to inhibit inflammation and apoptosis in diabetic retinopathy rats." (PMID 37819496, 2023). "Activation of SIRT1 by Resveratrol maintains the epithelial barrier by increasing the expression of TJ proteins ZO1, Occludin and Claudin1, while it negatively regulates MMP9 in diabetic retinopathy, and reduction of SIRT1 levels through oxidative stress confers an increase in MMP9." (PMID 39086962, 2022). "Researchers reported that Astragalus polysaccharide upregulates the expression of SIRT1 by inhibiting miR-204, ER stress, and apoptosis in high glucose-induced diabetic retinopathy and metabolic memory models, thereby delaying the development of diabetic retinopathy." (PMID 36091599, 2022). "Chronic treatment of SRT1720, an isoform-selective SIRT1 activator, has been reported to alleviate diabetic retinopathy by preventing cholesterol accumulation, inflammation, visual dysfunction, vascular degeneration, and neuro-degeneration in the retina of T2D mice." (PMID 34071497, 2021). "miR-195 regulates sirtuin 1 (SIRT1)-mediated tissue damage in diabetic retinopathy." (PMID 33255227, 2020). "The role of ncRNA-mediated SIRT1 changes in diabetic retinopathy." (PMID 33537003, 2020). "The inhibition of the expression of type I PRMTs, especially PRMT1 and PRMT4, and increased SIRT1 could be therapeutic approaches for diabetic retinopathy." (PMID 26583059, 2015).
diabetic retinopathy (continued). "Under HG conditions, miR-221, miR-377, miR-34a, miR-30b, and miR-29b-3p are upregulated, leading to SIRT1 downregulation, pathological proliferation, migration, inflammation, apoptosis, senescence, oxidative stress, and angiogenesis in RMECs, contributing to the pathogenesis of diabetic retinopathy." (PMID 39598406, 2024). "Therefore, the inhibition of type I PRMT expression, especially PRMT1 and PRMT4, and the increase in SIRT1 expression could be therapeutic approaches for diabetic retinopathy." (PMID 26583059, 2015). "The aim of the work was to design and optimize SNEDDS for the ocular delivery of two natural SIRT-1 agonists, resveratrol (RSV) and melatonin (MEL), with potential implications for treating diabetic retinopathy." (PMID 38258134, 2024). "Self-nanoemulsifying drug delivery systems (SNEDDS) were developed and tested for efficient ocular delivery of Sirtuin-1 (SIRT-1) agonists, resveratrol (RSV), and melatonin, for potential applications in diabetic retinopathy treatment." (PMID 38675402, 2024). "For the first time, we highlighted the pathogenesis of metabolic memory about miR-204/SIRT1 axis and the potential of APS in drug development on metabolic memory-mediated diabetic retinopathy." (PMID 31894851, 2020). "SIRT1 is key to reduced NFkB, COX2, and other deleterious pathways involved in diabetic retinopathy." (PMID 31159195, 2019). "Moreover, SIRT1 modulates transcription factors such as NF-κB, HIF-α, and FOXO1 to reduce the severity of diabetic retinopathy." (PMID 41011644, 2025). "Distribution of SIRT1 (rs3758391 T > C) genotypes and alleles in T2DM patients without complication, diabetic neuropathy, diabetic retinopathy and controls." (PMID 39474345, 2024). "However, in an experimental diabetic retinopathy cell model, melatonin delays diabetic retinopathy (DR) progression by upregulating MEG3 and inhibiting model cell activation and pro-inflammatory cytokine production via the MEG3/miR-204/SIRT1 axis." (PMID 36267400, 2022). "Resveratrol can attenuate high glucose-provoked apoptosis in retinal capillary endothelial cells by activating SIRT1/AMPK/PGC1α signal transduction and is proposed to be an effective therapeutic agent to prevent the pathogenesis in the early stage of diabetic retinopathy." (PMID 34071497, 2021). "Whether BGP-15 may affect in this pathway beside HSP72 either SIRT1 or MMP9 and thus the pathogenesis of diabetic retinopathy was still to be discovered." (PMID 32204537, 2020). "However, the role of SIRT1 rs3758391 variants in susceptibility to T2DM complications, including diabetic neuropathy and diabetic retinopathy have not been studied." (PMID 39474345, 2024).
Glucose intolerance (41 papers, 2008 to 2025). Glucose intolerance (GI) can be defined as dysglycemia that comprises both prediabetes and diabetes. "Genetic deletion of SIRT1 from adipocytes leads to increases adiposity, exaggerated insulin resistance, glucose intolerance, inflammation and predisposes to metabolic disfunction in mice on short-term HFD." (PMID 38116204, 2023). "Selective overexpression of SIRT1 in ß-cells improves glucose metabolism in mice, while selective deletion causes glucose intolerance." (PMID 32486051, 2020). "This decrease in Sirt1 levels might be related to the induction of AS-associated oxidative stress driven by glucose intolerance and exposure to saturated fatty acids, as both were shown to reduce Sirt1 expression in human monocytes." (PMID 22493735, 2012). "The novel findings of the present study are that Sirt1 overexpression protects against WD‐induced large artery stiffening and that this is associated with a protection against arterial wall expression of structural components, extracellular matrix enzymes, and glucose intolerance." (PMID 35561022, 2022). "Disruptions in SIRT1 activity are linked to T2DM and other metabolic dysfunctions; decreased SIRT1 expression and activity have been linked to poor insulin signaling and glucose intolerance." (PMID 38931292, 2024). "Studies in rodents have demonstrated that impaired SIRT1 expression reduced autophagic flux, leading to lipid accumulation, lipotoxicity, and glucose intolerance in the SKM and liver." (PMID 37627494, 2023). "Intestinal epithelial cell-specific Sirt1 KO mice exhibit glucose intolerance during oral glucose tolerance tests under calorie-restriction conditions." (PMID 36986224, 2023). "Maternal SIRT1 overexpression also reversed glucose intolerance, and normalised abnormal fat morphology and the expression of dysregulated lipid metabolism markers, including SIRT1." (PMID 33027895, 2020). "Further confirming the key role of SIRT1 in adipose tissue homeostasis, a recent manuscript described how adipose-specific overexpression of human SIRT1 protects mice against age-related glucose intolerance." (PMID 24567900, 2014). "Along this line of reasoning, β-cell specific overexpression of SIRT1 alone prevents HFD-induced glucose intolerance." (PMID 24567900, 2014). "To further test the role of Sirt1 in this axis, we bred 1α(OH)ase−/−Sirt1Tg mice to specify whether overexpression of Sirt1 could normalize the glucose intolerance observed in 1α(OH)ase−/− mice." (PMID 35132380, 2022). "Likewise, Sirt1 overexpression also protects against WD‐induced glucose intolerance." (PMID 35561022, 2022). "The genetic over-expression of SIRT1 or its activation by resveratrol treatment protects against HFD-induced hepatosteatosis and glucose intolerance as well as alcoholic diet-induced liver injury and fibrosis." (PMID 33193730, 2020). "HFD induced glucose intolerance in WT and HET mice, with glucose homeostasis being slightly impaired in SIRT1 HET mice at baseline." (PMID 31500354, 2019). "Also, hepatic knockout of SIRT1 fails to alter serum insulin and leptin levels and shows normal insulin sensitivity and fuel metabolism in white adipose tissue and muscle and thus does not cause systemic glucose intolerance." (PMID 24009212, 2013). "Interestingly, overexpression of SIRT1 in the HFD-parent attenuated metabolic disorders in the mice offspring, reversing glucose intolerance and normalizing fat morphology with increasing SIRT1 levels." (PMID 33806509, 2021).